SHBG (sex hormone binding globulin)
Diseases named in the same sentence as SHBG in open-access papers (continued):
Sharing a sentence is not in itself a finding about the gene and the disease.
Hyperinsulinemia (continued). "Both hypersecretion of LH and hyperinsulinemia cooperate to increase ovarian theca cell androgen production contributing to androgen dependent hirsutism also by suppression of hepatic secretion of sex hormone binding globulin (SHBG), which increases the bioavailability of circulating testosterone." (PMID 27725832, 2016). "Hyperinsulinemia augments androgen synthesis in theca cells via interactions with insulin and IGF-1 receptors, suppresses the formation of hepatic sex hormone-binding globulin (SHBG), and elevates the bioavailability of androgens." (PMID 41010046, 2025). "Hyperinsulinemia enhances the adrenal steroid response to ACTH stimulation and reduces the synthesis of sex hormone-binding globulin (SHBG) in the liver, which leads to an increase in total androgen and free androgen levels." (PMID 38348417, 2024). "Precisely, hyperinsulinemia, which commonly presents in PCOS due to IR, downregulates the SHBG gene transcription and, therefore, the SHBG production." (PMID 38353886, 2024). "This implies that insulin inhibits the secretion of SHBG from the liver, resulting in high levels of free androgens, and explains why obese PCOS women with hyperinsulinemia have low SHBG levels." (PMID 37062827, 2023). "Furthermore, IR-hyperinsulinemia could contribute to anovulation through stimulatory effects of luteinizing hormone (LH) on androgen production in the ovarian theca cells and via inhibition of sex hormone-binding globulin (SHBG) production by hepatocytes." (PMID 35881588, 2022). "Hyperinsulinemia increases the adrenal steroid response to ACTH stimuli and decreases the synthesis of sex hormone binding globulin (SHBG) in the liver, with a consequent increase of both total and free androgen levels." (PMID 35456928, 2022). "Hyperinsulinemia induces the hyperandrogenism of PCOS by increasing ovarian androgen synthesis (especially testosterone and androstenedione) and decreasing sex hormone binding globulin (SHBG) buildup (a critical driver of the free androgen index)." (PMID 36299963, 2022). "In the present study, the significantly lower levels of SHBG in PCOS obese patients compared to control participants, can be easily related to hyperinsulinemia, and increase in testosterone level." (PMID 34122339, 2021). "Among these factors are the severity of hyperinsulinemia and HA, the blood levels of the binding proteins for insulin, IGF-1 (IGFBP-1) and androgens (SHBG), and the blood levels of AMH and HDL-C." (PMID 33429918, 2021). "Hyperinsulinemia inhibits HNF-4α expression and reduces the synthesis and production of SHBG in the liver." (PMID 33139661, 2020). "Hyperinsulinemia along with hyperandrogenemia and enhanced levels of IGF-1 inhibit sex hormone-binding globulin secretion, which surges the levels of bioactive androgens and worsens the clinical manifestations of androgen excess in PCOS patients." (PMID 31970309, 2019). "In our own cohort, mostly AGA-born PA girls had early growth acceleration, hyperinsulinism, elevated IGF-1, and decreased SHBG concentrations, and as our current study indicates, also earlier pubertal development." (PMID 29163361, 2017). "Hyperinsulinemia, which is present in most cases of PCOS, increases androgen synthesis in theca cells and reduces the synthesis of hormone-binding proteins in the liver (SHBG, IGFBP-I)." (PMID 39410647, 2024). "Hyperinsulinemia elevates serum concentrations of free insulin-like growth factor-1 (IGF-1) and androgens, while simultaneously reducing insulin-like growth factor-binding protein 3 (IGFBP-3) and sex hormone-binding globulin." (PMID 36964104, 2023). "Hyperinsulinemia induces a decrease in insulin-like growth factor binding protein-1 and 2 (IGFBP-1 and 2) and reduces sex hormone binding globulin (SHBG) levels, resulting in an increase in free estrogen and androgen and insulin-like growth factor-1 (IGF-1) levels." (PMID 36755926, 2023).
Hyperinsulinemia (continued). "This may explain the molecular mechanism by which hyperinsulinemia downregulates HNF-4α expression, thereby reducing hepatic SHBG production by up-regulating ACC-lipogenesis." (PMID 33139661, 2020). "Hyperinsulinemia in PCOS stimulates androgen secretion by ovarian theca cells and increases the hormonally active free androgen fraction by reducing the hepatic production of SHBG." (PMID 23216997, 2012). "Hyperinsulinemia synergizes with LH on theca cells, upregulating CYP17A1 transcription and cytochrome P450 17α-hydroxylase (P450c17α) activity while simultaneously lowering hepatic sex hormone-binding globulin (SHBG) and insulin-like growth factor-binding protein-1 (IGFBP-1)." (PMID 41294822, 2025). "Additionally, hyperinsulinemia stimulates the hypothalamus to increase GnRH secretion, leading to an imbalanced LH/FSH ratio that disrupts follicular development and ovulation, while simultaneously suppressing hepatic production of SHBG." (PMID 40694958, 2025). "Hyperinsulinemia stimulates the production of ovarian androgens through its effects on the fully functional post-receptor MAP-K insulin pathway, and insulin also suppresses the hepatic production of SHBG, thereby accounting for the suppressed serum levels of SHBG in PCOS." (PMID 37361535, 2023). "Women with PCOS have hyperinsulinemia, which influences the hypothalamic-pituitary-gonadal axis, enhancing the luteinizing hormone (LH) secretion over follicle-stimulating hormone (FSH), reducing follicular maturation and sex hormone-binding globulin (SHBG), and producing ovarian androgen." (PMID 34754696, 2021). "In particular, the related hyperinsulinemia could induce an excess of androgens production in PCOS women through two different ways: first one is direct stimulation of ovaries to produce androgens, and the other one is the reduction of sex hormone binding globulin (SHBG) serum levels." (PMID 27642297, 2016). "Additionally, SHBG levels were significantly lower in hyperinsulinemic/obese adolescents with oligomenorrhea compared to those with PCOS, suggesting that SHBG alone may not be sufficient to reliably distinguish PCOS, particularly in the presence of hyperinsulinemia." (PMID 40861046, 2025). "Despite the severe hyperinsulinemia, she had normal triglyceride, high-density lipoprotein (HDL) cholesterol and sex hormone binding globulin (SHBG) level and there was no hepatosteatosis on ultrasonographic evaluation." (PMID 32018348, 2020). "In fact, hyperinsulinemia, independent of BMI, is a key contributor to PCOS pathogenesis as it results in augmented androgen production in the adrenal cortex and follicles via stimulation of LH secretion, while concomitantly reducing SHBG (sex hormone binding globulin) synthesis." (PMID 33396555, 2020).
diabetes (174 papers, 2005 to 2026). "Higher omics scores of SHBG and lower omics scores of Free T were associated with lower diabetes risk in both sexes; and higher E2 scores with higher incident hypertension risk only in men." (PMID 42094177, 2026). "Sex hormones also affect diabetes risk differently, with low testosterone and high estradiol-to-testosterone ratios increasing diabetes risk in men, whereas low estradiol and sex hormone-binding globulin (SHBG) levels are risk factors in women." (PMID 41531536, 2025). "We adjusted for confounders such as age, ethnicity, and type 2 diabetes mellitus status via multivariable logistic regression to determine the odds of hypothyroidism associated with SHBG levels." (PMID 40135042, 2025). "Further support for SHBG’s protective role comes from a longitudinal human study observing changes in SHBG and diabetes risk over the menopause transition." (PMID 41180177, 2025). "Previous studies have examined the usefulness of SHBG as a marker of the risk of this type of diabetes." (PMID 40427034, 2025). "SHBG levels are independently associated with the risk of metabolic syndrome such as diabetes, nonalcoholic fatty liver disease, and hypertension." (PMID 40453733, 2025). "The association between SHBG and metabolic syndrome implies a connection with IR.Although IR becomes significant over the course of diabetes, SHBG levels are inversely related to glycated hemoglobin (HbA1c), in normalindividuals." (PMID 39411775, 2024). "Adding sex steroids and SHBG to the fully adjusted main models had little influence, except for some attenuation of the inverse association with BMI in men with diabetes after adjustment for TT." (PMID 38234143, 2024). "Further studies are needed to elucidate the implications of high SHBG levels and diabetes risk in MLWH." (PMID 39055720, 2024). "Multiple studies confirm that SHBG has a direct effect on metabolic health and diabetes through SHBG polymorphisms and apolipoprotein B." (PMID 38660513, 2024). "SHBG levels are independently associated with the risk of diabetes, dementia, non-alcoholic fatty liver disease, hypertension, coronary heart disease, and ischemic stroke, all of which are associated with a higher risk of MetS." (PMID 39026336, 2024). "This study sought to investigate the correlation between serum sex hormone-binding globulin (SHBG) levels and nutrition indicators and the malnutrition exposure risk in men and postmenopausal women with type 2 diabetes mellitus (T2DM)." (PMID 39020340, 2024). "Specific single-nucleotide polymorphisms (SNPs) (such as rs6257, rs6259, and rs1799941) in the SHBG gene are risk factors for the development of diabetes." (PMID 39195702, 2024). "Another prospective study of 1462 Swedish women baseline aged 38 to 60 years with 12 years of follow-up found that low SHBG level was associated with a higher age-adjusted risk of developing diabetes mellitus." (PMID 38213908, 2024). "Previous clinical studies have indicated that low serum SHBG levels are associated with impaired glucose homeostasis and the increased risk of diabetes." (PMID 39195702, 2024). "SHBG partially mediates the inverse association between testosterone with diabetes; low testosterone is linked to diabetes via a bidirectional relationship with visceral fat, muscle, and bone." (PMID 37367840, 2023). "Type 2 diabetes mellitus was associated with the decrease of total testosterone (β: -0.021,95%CI: -0.032, -0.010, p<0.001) and sex hormone binding globulin (β: -0.048,95%CI: -0.065, -0.031, p<0.001)." (PMID 37900148, 2023). "In three population-wide prospective cohorts, it was consistently observed that lower plasma SHBG concentrations and higher T concentrations were associated with a lower risk of diabetes in women." (PMID 36767197, 2023). "Multiple reproductive hormones likely contribute to relations between reproductive factors and diabetes risk, including estradiol and SHBG." (PMID 36059005, 2022).
diabetes (continued). "Whereas increasing SHBG was associated with an increased risk of depression or ever having had cancer, increasing SHBG was associated also with a reduced risk of diabetes, hypertension, and cardiovascular disease." (PMID 36425465, 2022). "A report indicated that the total testosterone and sex hormone-binding globulin were negatively associated with diabetes in male, while the result from estrogen was inverse." (PMID 35135573, 2022). "A cross-sectional study estimated that U.S. national prevalence of low SHBG was 2.7% in women, which was linked with body mass index (BMI), excessive liver fat, diabetes, ethnicity, chronic obstructive pulmonary disease, coronary heart disease, and smoking." (PMID 35493382, 2022). "The association between low total testosterone and diabetes has been previously attributed to low SHBG observed commonly in T2DM." (PMID 34178211, 2021). "Carriers of the SHBG polymorphisms rs6257 and rs6259 present a higher risk of diabetes than carriers of other alleles and present low levels of SHBG." (PMID 34335746, 2021). "Studies have shown that low SHBG levels are predictive of higher risk for developing hypertension, type 2 diabetes mellitus (T2DM), and MetS in the general population." (PMID 33101409, 2020). "Other authors showed a positive relation between FSH concentration and sex hormone binding globulin expression (low SHGB is a well-known risk factor for diabetes) in postmenopausal women." (PMID 31467615, 2019). "SHBG is reduced in type 2 diabetes mellitus (T2DM), and the strength of the association is reduced, but not eliminated, after adjustment for age and body mass index (BMI)." (PMID 26761949, 2016). "After fully adjusting for age, current smoking status, BMI, systolic blood pressure, diabetes and blood cadmium levels, TT and SHBG levels were still positively associated with BLLs (model 3)." (PMID 27898110, 2016). "So, in our study, it indicated that, among the three androgen markers, serum SHBG was the most relevant factor associated with diabetes and prediabetes." (PMID 27583401, 2016). "Several studies showed that weight loss through calorie restriction and metformin treatment, in combination with lifestyle changes, increases serum SHBG levels in adolescents at risk for developing diabetes." (PMID 26761949, 2016). "In multinomial logistic regression, serum TT and SHBG were inversely associated with prediabetes and diabetes." (PMID 27583401, 2016). "In the further multinomial logistic regression analysis, similar to the result of diabetes group, TT and SHBG were inversely associated with the presence of prediabetes." (PMID 27583401, 2016). "In this population-based study, we observed that the VAI mirroring visceral adipose tissue dysfunction was significantly associated with lower total T, E2 and SHBG levels after adjusting for age, smoking, neck and hip circumference, diabetes and hypertension." (PMID 26796865, 2016). "As low levels of SHBG are also a strong predictor of the risk of type 2 diabetes mellitus, it is possible that miRNA 6767-5p has an important role in the metabolic manifestations of PCOS." (PMID 27677182, 2016). "High free E2 and lower SHBG were reported to significantly increase risk of developing diabetes in postmenopausal women." (PMID 25959422, 2016). "Multinomial logistic regression was used for the association of TT, SHBG and FT with prediabetes and diabetes, as well as prediabetes in age subgroups." (PMID 27583401, 2016). "Among 2654 male participants, increasing quartiles of either SHBG or TT were inversely associated with the presence of both prediabetes and diabetes after adjustment for age, residence area and economic status (P for trend<0.0001, model 1)." (PMID 27583401, 2016). "Lastly, the role of sex hormone binding globulin (SHBG) as a potential mediator between caffeinated coffee intake and reduced risk of diabetes among postmenopausal women has been proposed." (PMID 25978631, 2015).
diabetes (continued). "Increased SHBG levels were negatively associated with BMI, abdominal circumference and prevalence of diabetes." (PMID 24714992, 2014). "Genetic studies have defined a causal relationship between SHBG and type 2 diabetes mellitus in subjects of European ancestry." (PMID 29043159, 2013). "Our findings suggest that SHBG in women and testosterone in men are associated with diabetes in a Japanese population." (PMID 23066943, 2012). "We fitted conditional logistic regression models to examine the associations between SHBG and total testosterone levels with diabetes by sex." (PMID 23066943, 2012). "Second, we used the FLI, a validated surrogate maker for fatty liver, to examine the impact of fatty liver on the SHBG-diabetes association." (PMID 23066943, 2012). "For example, sexual hormone binding globulin (SHBG) levels were negatively associated with diabetes and diabetes related traits, and studies utilizing mendelian randomization with the SHBG gene provide evidence for a causal link." (PMID 22768041, 2012). "Emerging genome-wide association studies (GWASs) and Mendelian randomization (MR) analyses have provided new insights into the causal associations between genetically determined SHBG levels and type 2 diabetes mellitus (T2DM), coronary heart disease, breast cancer, asthma, and arthritis." (PMID 40728963, 2025). "This inverse association is suggested to be due to long-term diabetes, in which increased levels of sex hormone-binding globulin (SHBG) could reduce the testosterone levels, or due to elevated levels of growth factors among patients with diabetes." (PMID 41367482, 2025). "Similarly, a lower level of SHBG is correlated with increased risk of diabetes mellitus type 2 (DM 2) development." (PMID 40427034, 2025). "Furthermore, stable or increasing rates of change in SHBG were independently associated with a lower risk of diabetes compared to decreasing rates of change." (PMID 41180177, 2025). "Lastly, we construct and validate genetic scores and genetic risk scores (GS/GRSs) to estimate testosterone, SHBG levels, and hypogonadism and find significant associations with metabolic conditions, such as hyperlipidemia, gout, and diabetes, as well as cardiac and liver disorders." (PMID 40316537, 2025). "Furthermore, we reanalyzed the link between SHBG levels and MetS using the MetS criteria defined by the 2009 International Diabetes Federation, and the results confirmed a stable association between SHBG levels and MetS." (PMID 39026336, 2024). "Moreover, many studies showed an inverse association between circulating SHBG levels and the risk of diabetes." (PMID 39195702, 2024). "Previous literature has indicated that SHBG, rather than testosterone, might be a crucial metric associated with diabetes and metabolic syndrome, positioning SHBG as a viable metabolic risk biomarker." (PMID 38818507, 2024). "Furthermore, lower SHBG levels were associated with higher daily alcohol intake levels, higher BMI, and a higher risk of diabetes, CHD, and non-alcoholic fatty liver disease, - all of which contributed to elevated risk of MetS." (PMID 39026336, 2024). "Although PLS regression has been used to extract complex correlation features, further studies are needed to elucidate the relationship between sex hormones and SHBG and diabetes risk because the relationship between sex hormones and SHBG is highly dynamic and complex." (PMID 36767197, 2023). "In general, women tend to have higher SHBG levels than men while reduced SHBG concentrations in women may be associated with higher diabetes risk." (PMID 36012115, 2022). "However, we suggest that future study of the relation of FSH and diabetes risk should specifically address potential confounding or mediation by SHBG and estradiol." (PMID 36059005, 2022). "Elevated SHBG levels may indicate a polymorphism-mediated risk of diabetes that the SHBG gene may undergo." (PMID 36012115, 2022).